MIR191 (microRNA 191)
Synonyms: hsa-mir-191; MIRN191; miR-191
Gene: MicroRNA gene on chromosome 3 (49,020,618 to 49,020,709, reverse strand). Ensembl gene ENSG00000207605.
Gene Ontology:
Biological process: miRNA-mediated post-transcriptional gene silencing
Cellular component: RISC complex
Homologues: Orthologues: chimpanzee ptr-mir-191 (100% identical), rabbit MIR191 (98% identical), dog MIR191 (97% identical), macaque MIR191 (93% identical), pig ssc-mir-191 (84% identical), guinea pig MIR191 (77% identical), mouse Gm55600 (64% identical), tropical clawed frog xtr-mir-191 (63% identical).
Diseases named in the same sentence as MIR191 in open-access papers:
MIR191 is named in the same sentence as 2 diseases in open-access papers, as found by Europe PMC text mining. Sharing a sentence is not in itself a finding about the gene and the disease. The quoted sentences say what the papers report.
breast carcinoma (1 paper, 2025). "In turn, MIR-191 suppresses the expression of a number of genes, including SOX4 in breast carcinoma." (PMID 39796785, 2025).
MIR191 also shares sentences with these, for which no sentence is quoted: ovarian tumors (1 paper).